KLRF2 (killer cell lectin like receptor F2)
Description:
C-type lectin-like receptor involved in natural killer cell mediated cytotoxicity and cytokine secretion in keratinocytes via its interaction with CLEC2A. Triggers degranulation in a SYK-dependent manner and stimulates SYK phosphotyrosinylation without recruiting SYK directly.
Synonyms: NKp65
Tractability: Antibody: UniProt places it where antibodies can reach, with high confidence; its Gene Ontology location is reachable by antibodies, with high confidence; UniProt predicts a signal peptide or a membrane-spanning region.
Gene: Protein-coding gene on chromosome 12 (9,881,489 to 9,895,833, forward strand). Ensembl gene ENSG00000256797.
Subcellular location: Cell membrane
Gene Ontology:
Molecular function: protein binding; protein homodimerization activity
Biological process: natural killer cell degranulation; positive regulation of cytokine production
Cellular component: plasma membrane
Genetic constraint (gnomAD): Loss-of-function variants: 9 observed, 12.41 expected, observed/expected ratio (o/e) 0.72, 90% interval 0.44 to 1.26. The upper end of that interval is the gene's LOEUF score, 1.26, which puts it in group 5 of 6, group 1 being the genes least tolerant of losing a copy. Missense variants: 123 observed, 118.58 expected, observed/expected ratio (o/e) 1.04, 90% interval 0.89 to 1.21. Synonymous variants: 34 observed, 43.49 expected, observed/expected ratio (o/e) 0.78, 90% interval 0.59 to 1.04.
Homologues: Orthologues: chimpanzee KLRF2 (97% identical), macaque KLRF2 (84% identical), dog KLRF2 (61% identical), zebrafish si:ch211-170d8.8 (21% identical), zebrafish si:dkey-26c10.5 (17% identical), Caenorhabditis elegans clec-146 (17% identical), zebrafish si:ch211-193e13.5 (16% identical), Drosophila melanogaster rgn (16% identical), Caenorhabditis elegans clec-196 (12% identical). Paralogues in human: KLRB1 (22% identical), KLRF1 (22% identical), CLEC12B (21% identical), CLEC2D (21% identical), CLEC7A (21% identical), OLR1 (21% identical), CLEC12A (20% identical), CLEC1A (18% identical), CLEC9A (18% identical), KLRD1 (18% identical), CD69 (17% identical), KLRG1 (17% identical), and 11 more.
Diseases named in the same sentence as KLRF2 in open-access papers:
KLRF2 is named in the same sentence as 5 diseases in open-access papers, as found by Europe PMC text mining. Sharing a sentence is not in itself a finding about the gene and the disease. The quoted sentences say what the papers report.
squamous cell carcinoma (1 paper, 2025). A carcinoma arising from squamous epithelial cells. "Recently, Magnaldo and colleagues described an antitumoral involvement of the NKp65-KACL axis, namely the restriction of squamous cell carcinoma invasion in Xeroderma pigmentosum patients which led to the notification of the KLRF2 gene in the DISGENET database." (PMID 40802609, 2025).
KLRF2 also shares sentences with these, for which no sentence is quoted: inflammatory skin disease (1 paper); psoriasis (1); tumor (1); xeroderma pigmentosum (1).